LHCGR (luteinizing hormone/choriogonadotropin receptor)
Diseases named in the same sentence as LHCGR in open-access papers (continued):
Sharing a sentence is not in itself a finding about the gene and the disease.
germ cell tumor (2 papers, 2020 to 2024). A benign or malignant, gonadal or extragonadal neoplasm that originates from germ cells. "Serum concentrations of soluble LHCGR could not distinguish 4 patients with GCNIS and 216 patients with testicular germ cell tumors (TGCTs) from 297 infertile or 148 healthy young men." (PMID 32466562, 2020).
Oligomenorrhea (2 papers, 2016 to 2024). Infrequent menses (less than 6 per year or more than 35 days between cycles). "Lower expression of LHCGR in PCOS CCs may be a response to increased LH levels, oligomenorrhea, resistance to LH, infertility." (PMID 28004769, 2016).
ovarian hyperstimulation syndrome (2 papers, 2013 to 2022). A complication of ovulation induction in infertility treatment. "hCG can cause severe complications like ovarian hyperstimulation syndrome (OHSS) due to its prolonged half-life and potent stimulation of LHCGR." (PMID 36072937, 2022).
ovarian tumor (2 papers, 2020 to 2023). "Studies in LHCGR knock out mice (LuRKO) have not reported increased ovarian tumor development but reported a bone phenotype." (PMID 33374698, 2020).
prostate carcinoma (2 papers, 2020 to 2022). A carcinoma that arises from epithelial cells of the prostate gland. "Notably, LHCGR expression was only detected in a fraction of the prostatic cancer epithelial ducts." (PMID 32881970, 2020).
adrenocortical carcinomas (1 paper, 2019). "In the current study, we confirmed the LHCGR expression in H295R adrenocortical carcinoma cells and showed that hCG stimulation resulted in mitotic effect." (PMID 30400009, 2019). "We found that human adrenocortical carcinomas and mouse adrenocortical tumors expressed GNRHR and LHCGR mRNA and protein at variable levels, probably due to the well-known high heterogeneity of the tumors." (PMID 30400009, 2019). "In situ hybridization and qPCR analysis of human adrenocortical carcinomas (n = 11–13) showed expression of GNRHR in 54/73%, LHCGR in 77/100% and FSHR in 0%, respectively." (PMID 30400009, 2019). "In order to assess whether the adrenocortical carcinoma samples express GNRHR, LHCGR and FSH expression was studied using a commercial in situ hybridization RNAscope kit with single transcript resolution." (PMID 30400009, 2019). "We analyzed the expressions of receptors of gonadotropin-releasing hormone (GNRHR), luteinizing hormone/chorionic gonadotropin (LHCGR) and follicle-stimulating hormone (FSHR) in human adrenocortical carcinomas and assessed their response to GnRH antagonist therapy." (PMID 30400009, 2019).
aldosteronoma (1 paper, 2023). "This case demonstrates transient and repeated episodes of primary aldosteronism during pregnancies secondary to the ectopic expression of LHCGR in the patient’s aldosteronoma." (PMID 36926028, 2023).
Angiofibroma (1 paper, 2024). A benign neoplasm of fibrous tissue in which there are numerous small and large, frequently dilated, vascular channels. "The patterns of puncta in individual cells from patient #2420 are noticeably different from those of JA patients with fully mature angiofibroma, ranging from some few nuclear and subcellular LHCGR puncta to large labeled regions that cover most of the DAPI-stained nuclei." (PMID 39056799, 2024).
endometrial adenocarcinoma (1 paper, 2024). "Patients with a malignant endometrial adenocarcinoma have been found to benefit from treatments with inhibitors of either LHCGR or the vascular endothelial growth factor receptor 2 (VEGFR2)." (PMID 39056799, 2024).
Hyperinsulinemia (1 paper, 2025). An increased concentration of insulin in the blood. "Hyperinsulinemia is also theorized to increase the production of androgens in patients with PCOS, though this is through a process independent of the mechanism involving the LHCGR gene." (PMID 40535332, 2025).
Ovarian cyst (1 paper, 2010). The presence of one or more cysts of the ovary. "Women carrying homozygous inactivating LHCGR mutations have hypergonadotropic hypogonadism with primary amenorrhea or oligoamenorrhea, cystic ovaries, and infertility." (PMID 20593028, 2010). "Mutations of the LHCGR and FSHR genes may result in the development of ovarian cysts or hyperfunction, however in this study we did not identify mutations in either of these genes." (PMID 20593028, 2010).
ovarian disorder (1 paper, 2022). A disease involving the ovary. "If this is the case, the positive feedback regulation between LHCGR and BMAL1 will expand the ovarian disorder induced by hypoxia." (PMID 36620217, 2022).
pheochromocytoma (1 paper, 2023). "More recently, it was shown that life-threatening adrenergic myocarditis during pregnancy resulted from ectopic expression of LHCGR in a pheochromocytoma in which placental HCG stimulated epinephrine secretion." (PMID 36926028, 2023).
precocious puberty (1 paper, 2022). Unusually early sexual maturity. "We described a boy presenting with an early and severe gonadotropin-independent precocious puberty carrying a patrilineal inherited p.Ala568Val mutation in the LHCGR which, therefore, has not been reported in the Chinese population." (PMID 35909557, 2022).
primary aldosteronism (1 paper, 2023). An endocrine disorder characterized by excessive production of aldosterone by the adrenal glands. "The involvement of somatic CTNNB1 mutations in the induction of LHCGR and GnRHR ectopic expression and pregnancy-LH/HCG stimulated primary aldosteronism has been questioned." (PMID 36926028, 2023). "Finally, even though genetic somatic testing could not be performed in our patient, further studies should be aimed at trying to better understand the pathophysiological mechanisms leading to the expression and activation of ectopic LHCGR in primary aldosteronism." (PMID 36926028, 2023).
Primary amenorrhea (1 paper, 2005). "Partial or complete inactivation of the LHCGR gene due to a naturally occurring somatic mutation within the coding sequence could be responsible for the increase in serum LH concentrations in leydig cell hypoplasia, male hypogonadism, and primary amenorrhea." (PMID 15969756, 2005).
seizure disorder (1 paper, 2010). "In our cohort, only one subject had a seizure disorder (subject 1), although his 5 Mb deletion encompassed the entire NRXN1 gene as well as the genes for follicle-stimulating hormone receptor (FSHR), luteinizing hormone/choriogonadotropin receptor (LHCGR), and Stoned B-like factor (STN1)." (PMID 20468056, 2010).
serous ovarian cancer (1 paper, 2020). "An LHCGR antibody (LS-C334599, Sapphire Bioscience) detected major bands at ∼65 kDa, ~75 kDa and ∼100 kDa in all serous ovarian cancer cell lines." (PMID 33374698, 2020). "Other studies have reported LHCGR expression in mouse ovary between 66 kDa and 70 kDa, which is close to the ~65 kDa and ~75 kDa bands seen in the serous ovarian cancer cell lines and normal human ovary in our study." (PMID 33374698, 2020). "In addition, we investigated the effect of FSHR and LHCGR siRNA knockdown on the pro-metastatic behavior of serous ovarian cancer cells in vitro." (PMID 33374698, 2020). "Knockdown of FSHR or LHCGR expression increased invasion of serous ovarian cancer cells." (PMID 33374698, 2020). "Two serous ovarian cancer cell lines, OVCAR3 and COV362, which expressed both FSHR and LHCGR, were selected for the gonadotropin receptor knockdown and invasion studies below." (PMID 33374698, 2020).
skin tumor (1 paper, 2017). "Also, LHCGR is expressed by the BRCA1 conditional knockout mouse skin tumor tissue." (PMID 28869585, 2017).
testicular cancer (1 paper, 2020). A primary or metastatic malignant neoplasm that affects the testis. "Here, we investigated the expression of LHCGR in GCNIS, TGCTs, and TGCT-derived cells lines and the effects of LHCGR activation on proliferation of testicular cancer cell lines in vitro and in two tumor xenograft mouse models." (PMID 32466562, 2020).
trisomy 21 (1 paper, 2023). A chromosomal disorder consisting of the presence of an extra chromosome 21. "In trisomy 21-affected pregnancies, the synthesis and the expression of the mature receptor of hCG, LHCGR, are modified and a soluble fraction of LHCGR may circulate in the maternal blood." (PMID 37108840, 2023).
tumor (17 papers, 2011 to 2025). "High tumor expression of LHCGR and GNRHR in APAs with CTNNB1 (and GNA11/Q) mutations has been a rationale for the link between the disease onset and pregnancy, menopause, or puberty." (PMID 38505749, 2024). "FSHR expression was observed in cancer cells, tumor associated stroma and blood vessels, whilst focal LHCGR expression was present predominately in the tumor cells." (PMID 33374698, 2020). "Decreased LHCGR protein expression and LHCGR mRNA expression were associated with high tumor grade and reduced patient survival in EOC." (PMID 33374698, 2020). "The gene LHCGR was associated with tumor metastasis that involved in cell growth and neoangiogenesis, and plays an important role in luteinizing hormone (LH) receptors, which may impact on the tumorigenesis of ECs." (PMID 29297280, 2017). "A cell density of LHCGR+ CD271+ cells > 5 cells/mm2 (median of the lowest 1st quartile of patient #1041) seemed to indicate a fully developed tumor." (PMID 39056799, 2024). "As a possible pathogenesis of APA harboring these double mutations, an association with pregnancy, menopause, or puberty has been proposed based on the disease onset and increased tumor expression of luteinizing hormone/choriogonadotropin receptor (LHCGR)." (PMID 38505749, 2024). "This led us to investigate expression of LHCGR in PCa derived cell lines, PCa tissue from patients, and test the effect of LH and hCG on tumor growth and steroidogenesis." (PMID 32881970, 2020). "In contrast, patients that exhibited both high FSHR and high LHCGR tumor scores had the best survival outcome." (PMID 33374698, 2020). "One tumour with a CTNNB1-mutation was found to have substantially higher expression of both GNRHR and LHCGR than the other studied tumours." (PMID 31000732, 2019). "Since hCG is strongly involved in vascularization via LHCGR, the presence of both hCG and LHCGR could potentially provide positive hormonal feedback to induce tumor vascularization and cell proliferation leading to JA growth." (PMID 39056799, 2024). "However, the pathophysiologic role of high tumor expression of LHCGR and GNRHR mRNA in our case is unclear since her disease onset was not directly associated with pregnancy or menopause." (PMID 38505749, 2024). "However, patients that exhibited both low FSHR and LHCGR tumor IR scores had the poorest survival outcome." (PMID 33374698, 2020). "IHC was performed on the tumor tissue to detect the expression of LHCGR, MC2R and GPER-1." (PMID 32393232, 2020). "Our analysis showed that LHCGR was the most common DE gene found among the tumor samples." (PMID 21483740, 2011). "Moreover, the comparison for case (b) revealed LHCGR (luteinizing hormone/choriogonadotropin receptor; ID: 3973), a gene that also appeared to be the most common DE gene among the tumor samples." (PMID 21483740, 2011). "Finally, exploring LHCGR expression and its truncated forms may open new avenues for understanding tumor biology and therapeutic targeting." (PMID 40723290, 2025). "Therefore, the activation of LHCGR could act as a trigger for angiogenesis in this benign sex-specific tumor." (PMID 39056799, 2024). "Therefore, the co-existence of stem cells and LHCGR+ cells in JA tissue could result in positive hormonal feedback inducing tumor vascularization and cell proliferation, thus ultimately leading to JA growth." (PMID 39056799, 2024). "Due to the physiological changes in LH levels during adolescence, LHCGR expression could indicate the onset of tumor development and also explain the spontaneous regression of JA at the end of puberty, despite the fact that not all JA patients are affected in early childhood or puberty." (PMID 39056799, 2024). "mRNA for the hormone receptor LHCGR was previously identified in JA tissue by RT-PCR and could represent a new candidate to investigate the hypothesis of hormonal imbalance in this benign fibrovascular tumor in the nasal cavity." (PMID 39056799, 2024).
tumor (continued). "Ideally, future studies examining predictive value of the LHCGR should have increased sample size and combine information about LHCGR expression in prostatic tissue with serum levels of LHCGR to determine whether it is a marker of LHCGR abundance in the tumor or a proxy for something else." (PMID 32881970, 2020). "Hence, the current study aimed to analyze how GPER may interact with the FSHR/LHCGR system in EOC and whether the prognostic significance of GPER in EOC cases (n = 151) may be dependent on the FSHR/LHCGR immunophenotype of the tumor." (PMID 23951246, 2013). "Our present case also showed elevated expression of LHCGR and GNRHR mRNA in the tumor compared with that in adjacent adrenal." (PMID 38505749, 2024). "In agreement with previous studies, LHCGR and GNRHR mRNA levels were also elevated within the tumor compared with those in adjacent normal adrenal (148-fold and 56-fold, respectively)." (PMID 38505749, 2024). "The same hCG-H isoform, together with hCGβ and hCGβ-H, can be detected in serum and urine of NST patients diagnosed with a choriocarcinoma subtype component, thus supporting pathological angiogenesis and tumor invasion, with no or low LHCGR involvement." (PMID 40723290, 2025). "There were no reads for LHCGR in tumor or control adrenals, despite the likely inclusion of the zona reticularis from the nontumorous adrenals." (PMID 39429164, 2024). "Immunohistochemistry (IHC) showed the tumor tissue that stained positive for luteinizing hormone (LH)/human choriogonadotropin (hCG) receptor (LHCGR), whereas negative for both melanocortin 2 receptor (MC2R) and G protein-coupled receptor-1 (GPER-1)." (PMID 32393232, 2020). "The link between LHCGR and tumor burden is of clinical interest but the clinical use of LHCGR may be questioned if LHCGR adds no additional clinical value to the unspecific LDH measurements." (PMID 32466562, 2020). "GPER was found to correlate with GnRs in tumor samples and more importantly to be a positive prognosticator in EOC patients characterized as LHCGR/FSHR negative." (PMID 23951246, 2013). "Finally, understanding the biological roles of hCG isoforms and their “canonical” (e.g., LHCGR) and “non-canonical” (e.g., TGF-βR) receptor interactions may help in understanding tumor biology and therapeutic targeting." (PMID 40723290, 2025).
cancer (7 papers, 2017 to 2025). A tumor composed of atypical neoplastic, often pleomorphic cells that invade other tissues. "Furthermore, LHCGR activity has been implicated in the induction and progression of some cancers." (PMID 39056799, 2024). "The discord between FSHR and LHCGR with their respective protein levels is surprising but may be due to differences in mRNA turnover in cancer cells compared to gonadal tissues, mRNA instability, or varied protein half-lives in different cell types." (PMID 33374698, 2020). "We detected GNRHR in 54%, LHCGR in 77% and FSHR in 0% of the cancer samples." (PMID 30400009, 2019).
neurodegenerative disease (1 paper, 2005). A disorder of the central nervous system characterized by gradual and progressive loss of neural tissue and neurologic function. "Indeed, the pathological activation of cerebral microglial cells abundantly expressing LHCGR, has been linked to Alzheimer's and other neurodegenerative diseases with high circulating LH." (PMID 15969756, 2005).
LHCGR also shares sentences with these, for which no sentence is quoted: Alzheimer disease (3 papers); hypogonadotropic hypogonadism (3); type 2 diabetes mellitus (3); benign ovarian tumors (2); benign tumors (2); endocrine disorders (2); gestational hypertension (2); Hypertension (2); Micropenis (2); Stillbirth (2); acute lymphoblastic leukemia (1); adrenal hyperplasia (1); adrenocortical hyperfunction (1); adrenocortical tumors (1); age-related macular degeneration (1); androgen insensitivity syndrome (1); anorchia (1); anovulation (1); Autoimmunity (1); bladder cancer (1); chronic endometritis (1); chronic myeloid leukemia (1); cognitive deficits (1); COVID-19 (1); disorder of sexual differentiation (1); endometrial cancer (1); Hirsutism (1); hyperaldosteronism (1); Hypergonadotropic hypogonadism (1); Hypokalemia (1).
A further 22 diseases each share a sentence with LHCGR in 1 paper.